MT2P1 (metallothionein 2 pseudogene 1)
Gene: Processed pseudogene on chromosome 4 (68,376,323 to 68,376,505, forward strand). Ensembl gene ENSG00000162840.
Diseases named in the same sentence as MT2P1 in open-access papers:
MT2P1 is named in the same sentence as 4 diseases in open-access papers, as found by Europe PMC text mining. Sharing a sentence is not in itself a finding about the gene and the disease. The quoted sentences say what the papers report.
hepatocellular carcinoma (1 paper, 2025). A malignant tumor that arises from hepatocytes. "Distinctively, pseudogene MT2P1 is universally transcribed in hepatocytes and presents a significant decrease in hepatocellular carcinoma (HCC)." (PMID 40407049, 2025).
liver cirrhosis (1 paper, 2025). "While the lower expression of MT2P1-RNA is positively related to a higher quantity of serum Alpha-fetoprotein (AFP) (p < .05), more advanced TNM stages (p < .05), more tumor microsatellite formation (p < .05), detectable invasion of venous (p < .05), and later liver cirrhosis stages (p < .05)." (PMID 40407049, 2025).
tumor (2 papers, 2024 to 2025). "According to the analysis of the online databases, the parental gene MT2A was also significantly decreased in HCC tumor tissues and was positively correlated with the pseudogene-derived MT2P1-RNA." (PMID 40407049, 2025). "The significant decrease of MT2P1-RNA in HCC prompted that its expression was modulated by some transcriptional or post-transcriptional mechanisms during tumor development." (PMID 40407049, 2025). "The dataset analysis of both the dreamBase and LCLE databases presented high MT2P1-RNA levels in the normal liver tissues and negligible transcription levels in the HCC tumor tissues." (PMID 40407049, 2025). "The detection of the patients’ specimens collected from our medical center also demonstrated a significant decrease of MT2P1-RNA in most of the HCC tissues, and only a small portion of the tumor tissues (6.32%, 6/95) presented the detectable MT2P1-RNA." (PMID 40407049, 2025). "The exclusion of genes like BCL2L10, OR10J6P, CDX2, and MT2P1 from the PPI network due to lack of interaction data may also warrant further investigation into their specific molecular functions or how their roles might be context-dependent within the tumor microenvironment." (PMID 39766765, 2024).
cancer (1 paper, 2025). A tumor composed of atypical neoplastic, often pleomorphic cells that invade other tissues. "All these findings strongly illustrated that the MT2P1-RNA exerts a potential anti-cancer function by influencing cell growth and maintenance in HCC." (PMID 40407049, 2025).